IDH2 (isocitrate dehydrogenase (NADP(+)) 2)
Description:
Plays a role in intermediary metabolism and energy production. It may tightly associate or interact with the pyruvate dehydrogenase complex.
Synonyms: IDH; IDH-2; D2HGA2; ICD-M; IDHM; IDP; IDPM; mNADP-IDH
Tractability: Small molecule: an approved drug acts on it; a structure with a bound ligand is known; a high-quality ligand is known. PROTAC: ubiquitination databases record sites on it; its protein half-life has been measured; a small molecule that binds it is known.
Target class: Enzyme; Oxidoreductase
Chemical probes: AGI-6780 (high quality)
Gene: Protein-coding gene on chromosome 15 (90,083,045 to 90,102,490, reverse strand). Ensembl gene ENSG00000182054.
Subcellular location: Mitochondrion
Subcellular location (Human Protein Atlas): Mitochondria
Pathways (Reactome):
Metabolism: Citric acid cycle (TCA cycle); Maturation of TCA enzymes and regulation of TCA cycle
Metabolism of proteins: Mitochondrial protein degradation
Organelle biogenesis and maintenance: Transcriptional activation of mitochondrial biogenesis
Gene Ontology:
Molecular function: isocitrate dehydrogenase (NADP+) activity; magnesium ion binding; NAD binding; oxidoreductase activity, acting on the CH-OH group of donors, NAD or NADP as acceptor
Biological process: 2-oxoglutarate metabolic process; carbohydrate metabolic process; isocitrate metabolic process; NADP+ metabolic process; tricarboxylic acid cycle; NADP+ biosynthetic process; negative regulation of glial cell migration; negative regulation of glial cell proliferation; negative regulation of matrix metallopeptidase secretion
Cellular component: extracellular exosome; mitochondrion; mitochondrial matrix; cytosol; peroxisome
Genetic constraint (gnomAD): Loss-of-function variants: 16 observed, 48.44 expected, observed/expected ratio (o/e) 0.33, 90% interval 0.22 to 0.5. The upper end of that interval is the gene's LOEUF score, 0.5, which puts it in group 2 of 6, group 1 being the genes least tolerant of losing a copy. Missense variants: 484 observed, 587.32 expected, observed/expected ratio (o/e) 0.82, 90% interval 0.76 to 0.89. Synonymous variants: 261 observed, 223.68 expected, observed/expected ratio (o/e) 1.17, 90% interval 1.05 to 1.29.
Gene-disease validity (ClinGen):
ClinGen rates the evidence that IDH2 causes each of these diseases.
mitochondrial disease (autosomal dominant): Definitive.
Homologues: Orthologues: chimpanzee IDH2 (99% identical), macaque IDH2 (99% identical), pig IDH2 (97% identical), guinea pig IDH2 (96% identical), mouse Idh2 (95% identical), rat Idh2 (95% identical), rabbit IDH2 (90% identical), tropical clawed frog idh2 (86% identical), dog IDH2 (85% identical), Caenorhabditis elegans idh-2 (65% identical), zebrafish idh2 (45% identical). Paralogues in human: IDH1 (63% identical).
Diseases named in the same sentence as IDH2 in open-access papers:
IDH2 is named in the same sentence as 249 diseases in open-access papers, as found by Europe PMC text mining. Sharing a sentence is not in itself a finding about the gene and the disease. The quoted sentences say what the papers report.
glioma (608 papers, 2010 to 2026). A benign or malignant brain and spinal cord tumor that arises from glial cells (astrocytes, oligodendrocytes, ependymal cells). "In particular, in some cancers with IDH1/IDH2 mutations, such as gliomas, cells become reliant on the de novo pyrimidine synthesis pathway." (PMID 40961924, 2025). "The paucity of evidence linking D2hgdh mutations with glioma occurrence is striking considering the wide-spread prevalence of IDH1/IDH2 mutations in these tumors." (PMID 40236175, 2025). "In high-grade gliomas with the mitochondrial IDH2 mutation, mutant IDH2 aberrantly produce 2-HG, which inhibits TETs, FTO, ALKBH5, and JMJDs." (PMID 41008904, 2025). "Mutations in IDH1 (~80% of grade II-III gliomas and secondary GBMs and ~5% of primary GBMs) and less frequently IDH2 are characteristic of secondary GBM and are associated with a better prognosis." (PMID 39936963, 2025). "Whereas IDH1 mutations are more frequent than IDH2 mutations in glioma, the reverse is true for AML." (PMID 40867259, 2025). "Most co-deleted gliomas are also mutated on IDH1/IDH2, which is associated with a better prognosis than IDH wildtype." (PMID 40564017, 2025). "IDH-mutant astrocytomas are diffusely infiltrating gliomas defined by mutations in the IDH1 or IDH2 genes." (PMID 40711574, 2025). "A mitochondrial-targeting nanotherapy has been reported to exert potent antitumor effects in high-grade IDH2-mutated glioma by disrupting the mitochondrial–epigenetic axis." (PMID 41008904, 2025). "IDH (isocitrate dehydrogenase) mutations, predominantly IDH1 and IDH2, are another critical molecular hallmark, commonly associated with lower-grade gliomas and better prognoses." (PMID 40636690, 2025). "The alterations in IDH1 or IDH2 are dominant gain-of-function mutations, which are considered to be a prognostic marker for gliomas." (PMID 40564198, 2025). "IDH1 and IDH2 mutations are significant genetic alterations found in various tumor entities, particularly in cholangiocarcinomas, gliomas, and hematological malignancies." (PMID 40075667, 2025). "Mutations associated with IDH1 and IDH2 ultimately led to the reclassification of gliomas, changing them from being glioblastomas to astrocytomas (even if high grade) and oligodendrogliomas by the World Health Organization (WHO) in 2021." (PMID 40564017, 2025). "The definition of glioblastoma was revised to differentiate it from grade-4 gliomas harboring IDH1/IDH2 mutations." (PMID 40867254, 2025). "In fact, the widespread occurrence of IDH1/IDH2 mutations in gliomas and acute myeloid leukemia has led to the successful development of FDA approved IDH inhibitors, which are now used in combination therapies to treat IDH1/IDH2-positive tumors." (PMID 40236175, 2025). "Specific IDH1 and IDH2 mutations are characteristic of distinct subtypes, including low‐grade gliomas, secondary GBMs, chondrosarcomas, intrahepatic cholangiocarcinomas, and certain hematologic cancers." (PMID 40546878, 2025). "In any case, the glioma therapeutic landscape has seen significant advances with the approval of vorasidenib by the FDA in August 2024 for grade 2 gliomas with IDH1/IDH2 mutations." (PMID 40864821, 2025). "A second interesting example is isocitrate dehydrogenases (IDH1 and IDH2), enzyme-encoding genes that are frequently mutated in gliomas, acute myeloid leukemia, cholangiocarcinoma, chondrosarcoma, and thyroid carcinoma." (PMID 40330550, 2025). "IDH1 and IDH2 (isocitrate dehydrogenase) mutations are hallmark features of lower-grade gliomas and secondary glioblastomas." (PMID 41311621, 2025). "IDH1 and also IDH2 gene mutations have been identified in several types of cancers, such as gliomas, conventional central and periosteal malignant cartilaginous tumours, cytogenetically normal acute myeloid leukaemia, and cholangiocarcinoma." (PMID 40182999, 2025).
glioma (continued). "This study found a higher incidence of IDH1/IDH2 mutations in insular gliomas, associated with smaller tumor size at onset and lower malignancy." (PMID 39766037, 2024). "According to recent clinical trial results (NCT04164901), vorasidenib’s ability to penetrate the brain and target mutations in IDH1 and IDH2 enzymes showed significantly improved PFS in patients with grade 2 glioma." (PMID 38539537, 2024). "Currently, the clinical effectiveness and safety profile of vorasidenib (AG-881), the first dual inhibitor of mIDH1 and mIDH2, in the treatment of glioma with IDH1/IDH2 mutation are being investigated." (PMID 39063158, 2024). "IDH1 and IDH2 mutations are important, class-defining mutations in gliomas that carry significant therapeutic and prognostic implications." (PMID 39876890, 2024). "Hypermethylation, in particular, is associated with mutations in genes like IDH1 and IDH2, which are frequently altered in cancers, such as acute myeloid leukemia, glioma, and chondrosarcomas (CSs)." (PMID 39590345, 2024). "Having IDH1 or IDH2 mutations is associated with improved survival as these gliomas respond better to temozolomide therapy." (PMID 39200342, 2024). "For example, adult gliomas are often driven by IDH1 or IDH2 mutations, while subsets of low-grade pediatric gliomas are driven by rearrangements in the transcription factor-encoding proto-oncogenes MYB or MYB like 1 (MYBL1)." (PMID 38353122, 2024). "IDH1 and IDH2 gene mutations and co-deletion of chromosome 1p and 19q are two important diagnostic factors for the prognosis of glioma patients." (PMID 38348047, 2024). "Mutations in the IDH1 and IDH2 genes are common in gliomas, particularly low-grade gliomas and secondary glioblastomas, and are usually associated with specific metabolic abnormalities." (PMID 39457636, 2024). "Patients with residual or recurrent grade 2 glioma characterized by an IDH1 or IDH2 mutation were randomly assigned to receive Vorasidenib or a placebo." (PMID 39123479, 2024). "Patients with high-grade gliomas carrying IDH1 or IDH2 mutations are also usually younger than those with IDH1/IDH2-wild-type glioma." (PMID 38891962, 2024). "Point mutations in isocitrate dehydrogenase 1 and 2 (IDH1/IDH2) genes identified in diffuse gliomas with different degrees of malignancy have become the main factor for molecular-based classification of gliomas." (PMID 39684714, 2024). "IDH1 and IDH2 mutations are also associated with a better prognosis and are often found in lower-grade gliomas and secondary GBMs, which generally progress more slowly than primary GBMs." (PMID 39767571, 2024). "IDH2 mutations are less prevalent in gliomas, rendering an IDH2 inhibitor less likely to be beneficial in this cohort." (PMID 39876890, 2024). "A well-recognized oncometabolite is 2-HG, resulting from mutations in the isocitrate dehydrogenase 1 (IDH1) and 2 (IDH2) enzymes in gliomas and acute myeloid leukemia (AML)." (PMID 39684900, 2024). "One of the first advancements was the detection of 1p/19q codeletion in oligodendrogliomas, as well as the finding of mutations in the IDH1 and IDH2 genes in gliomas." (PMID 38807869, 2024). "Mutations in the IDH1 and IDH2 genes are commonly found in certain types of tumors (particularly in brain tumors known as gliomas) and result in the production of an oncometabolite called 2-hydroxyglutarate (2-HG)." (PMID 39170262, 2024). "Previous work has shown that patients with grade II–IV gliomas harbouring IDH1 or IDH2 mutation had significantly longer overall survival than those without IDH mutation." (PMID 39767640, 2024). "The mutant enzymes, in particular, the IDH1 R132H and IDH2 R172K variants, have been widely studied in low- and high-grade gliomas." (PMID 39457600, 2024). "IDH1 mutations occur in over 70% of LGG and GBM that progress from LGG and IDH2 mutation occur in less than 5% in gliomas." (PMID 39208202, 2024).
glioma (continued). "Mutations in the IDH1 and IDH2 genes strongly correlate with the development of glioma, acute myeloid leukemia, chondrosarcoma, intrahepatic cholangiocarcinoma, and angioimmunoblastic carcinomas of T-cell lymphomas." (PMID 38674026, 2024). "The R172K mutation in the IDH2 enzyme is related to different malignancies, including gliomas, chondrosarcomas, and myeloid leukemia, among others." (PMID 39457600, 2024). "IDH1 and IDH2 mutational status is a critical biomarker with diagnostic, prognostic, and treatment implications in glioma." (PMID 38796421, 2024). "Another study analyzed 811 glioma samples and identified only 3 of 266 (1.1%) astrocytomas harbored IDH2-mutation." (PMID 38012788, 2023). "Mutations in the isocitrate dehydrogenase genes (IDH1 and IDH2) define a unique glioma subtype associated with an immunosuppressive tumor microenvironment." (PMID 37543576, 2023). "Roughly 70% of grade 2–3 gliomas harbor mutations in either IDH1 or its mitochondrial counterpart IDH2." (PMID 36765553, 2023). "The most advanced clinical trial design is a phase 3, multicentre, randomised, double-blind, placebo-controlled study of AG-881 in subjects with residual or recurrent grade 2 glioma with an IDH1 or IDH2 mutation." (PMID 37296846, 2023). "Mutations in IDH1 and IDH2 are also common in gliomas, AML, chondrosarcomas, and cholangiocarcinoma." (PMID 36979633, 2023). "IDH1 and IDH2 mutations are found to be mutually exclusive in gliomas, and the presence of mutations in IDH1/IDH2 is associated with a favorable prognosis." (PMID 37371331, 2023). "Based on their molecular profile, a significant proportion of adult-type gliomas can be subtyped by IDH (IDH1 or IDH2) and ATRX mutation status, as well as 1p19q codeletion." (PMID 38106649, 2023). "In gliomas carrying mutations in genes encoding isocitrate dehydrogenase 1 (IDH1) or 2 (IDH2), microglia-derived TAMs are more dominant compared to wild-type gliomas." (PMID 37234776, 2023). "For example, mutations in the genes encoding isocitrate dehydrogenase (IDH) 1 and 2 (IDH1 and IDH2) account for approximately 80% of grade-2 gliomas and represent one of the fundamental and earliest molecular events in the genesis of these tumors." (PMID 37372381, 2023). "IDH1 and IDH2 mutations have long been established in the molecular pathology of gliomas, and now form a core aspect of their diagnostic classification." (PMID 37444417, 2023). "In 2016 WHO categorization, codeletion of chromosomal arms 1p/19q (1p/19q codeletion) and isocitrate dehydrogenase 1 or 2 (IDH1 or IDH2) were included in the diagnostic typing for glioma classification." (PMID 36627482, 2023). "At present, molecular pathological features (such as mutation status of isocitrate dehydrogenase gene IDH1 or IDH2) are used to classify adult glioma." (PMID 37698534, 2023). "It has three isoenzymes encoded by five genes, with IDH-1 and IDH-2 involved in developing human Gliomas." (PMID 37193447, 2023). "Another ongoing clinical trial is being conducted on IDH1 or IDH2 mutation-bearing adult glioma patients to test if nivolumab (anti- PD-1 antibody) stops tumor growth and provides long-lasting control of the tumor." (PMID 37274252, 2023). "In conclusion, the discovery of mutations in the IDH1 and IDH2 genes has revolutionized our understanding of lower-grade gliomas and opened up new avenues for diagnosis and treatment." (PMID 37212938, 2023). "Patients with gliomas carrying mutations in either IDH1 or IDH2 enzymes have a relatively favorable survival, compared with patients with gliomas with wild-type IDH1/2 genes." (PMID 36959545, 2023). "A brain lesion biopsy revealed a high-grade infra-tentorium IDH-1 and IDH-2 wild-type glial tumor, GFAP and Olig2 positive and histone H3‐K27M mutation-negative (glioblastoma, grade 4 WHO 2021)." (PMID 37692853, 2023).
glioma (continued). "IDH1 and IDH2 are frequently mutated in multiple types of human cancers, including glioma, acute myeloid leukaemia, cholangiocarcinoma, chondrosarcoma, and thyroid carcinoma." (PMID 37980418, 2023). "Although mutations of either IDH1 or IDH2 in gliomas are heterozygous, they have an impact on drug resistance as both IDH1 and IDH2 form homodimers to exert their catalytic function and mutant homodimers and heterodimers are inactive." (PMID 38068493, 2023). "The discovery of mutations in the IDH1 and IDH2 genes in gliomas has significantly impacted the classification and treatment of these tumors." (PMID 37212938, 2023). "IDH1mts occur in more than 70% of what was formerly termed “low-grade” gliomas and up to 20% of “higher-grade” tumors; IDH2 mutations have been found in about 4% of gliomas." (PMID 36968138, 2023). "Although numerous somatic mutations have been identified in IDH1/2 in tumors, there appears to be a predilection for specific binding site “hotspot” mutations (Arg 132 for IDH1, Arg 172 for IDH2) in certain diseases such as leukemia and glioma." (PMID 37371524, 2023). "DNA methylation patterns were associated with the mutations in IDH1 or IDH2 in lower grade gliomas, and mutations in histone 3 in pediatric high‐grade gliomas." (PMID 35338570, 2022). "Mutations in isocitrate dehydrogenase 1 (IDH1) and IDH2 drive the development of gliomas, which occur in most low-grade gliomas and secondary high-grade gliomas, and they enable the isocitrate dehydrogase (NADP+) activity." (PMID 36561336, 2022). "We analysed DNA from FFPE tumor samples of 58 glioma patients for mutations involving codon 132 of IDH1 or codon 172 of IDH2." (PMID 35361262, 2022). "In the past few years, various somatic point mutations of isocitrate dehydrogenase (IDH) encoding genes (IDH1 and IDH2) have been identified in a broad range of cancers, including glioma." (PMID 36188571, 2022). "Mutations in IDH were first reported in colon cancers; however, several studies have now reported mutations in IDH1 and IDH2 in several cancers, including gliomas, intrahepatic acute myeloid leukemia, and chondrosarcoma." (PMID 36160383, 2022). "Neomorphic mutations in isocitrate dehydrogenase (IDH) enzymes (arginine 132 for IDH1 and arginine 172 for IDH2) are found in 70% of gliomas and are highly associated with favorable outcomes of glioma patients." (PMID 35216362, 2022). "Mutations in isocitrate dehydrogenase 1 (IDH1) and IDH2 are oncogenic drivers to a variable extent in several tumors, including gliomas, acute myeloid leukemia (AML), cholangiocarcinoma, melanoma, and thyroid carcinoma." (PMID 34997121, 2022). "In 2016, the World Health Organisation (WHO) adopted isocitrate dehydrogenase 1 (IDH1) and isocitrate dehydrogenase 2 (IDH2) single nucleotide variants (SNVs) into its classification of gliomas." (PMID 36286062, 2022). "Previous studies have reported that IDH1 and IDH2 mutations were closely related to the prognosis of glioma patients." (PMID 35559020, 2022). "Perhaps the most established examples are the mutations found in in Isocitrate Dehydrogenase 1 (IDH1) and IDH2 that cause a major subset of gliomas." (PMID 35379950, 2022). "On the other hand, less than 1% of gliomas harbor IDH2 hotspot mutations, mostly occurring at arginine 172 (IDH2R172H mutation) or arginine 140 (IDH2R140 mutation)." (PMID 35267433, 2022). "When the IDH2 variant occurs in gliomas, in almost all of the cases, it consists of a substitution of the arginine at codon 172, which is the exact residue analogous to Arg132 in IDH1." (PMID 35456430, 2022). "Mutations in the gene encoding isocitrate dehydrogenase 1 (IDH1) and 2 (IDH2) were identified across several cancer types including gliomas, chondrosarcoma, and hematological malignancies." (PMID 35158978, 2022). "Mutations in IDH1 and IDH2 are among the most well-studied metabolic disturbances in gliomas, including GB." (PMID 35806212, 2022).